ZNF665 (zinc finger protein 665)
Description:
May be involved in transcriptional regulation.
Synonyms: ZFP160L; FLJ14345
Tractability: PROTAC: ubiquitination databases record sites on it.
Gene: Protein-coding gene on chromosome 19 (53,159,213 to 53,193,386, reverse strand). Ensembl gene ENSG00000197497.
Subcellular location: Nucleus
Subcellular location (Human Protein Atlas): Nuclear membrane
Pathways (Reactome):
Gene expression (Transcription): Generic Transcription Pathway
Gene Ontology:
Molecular function: DNA-binding transcription factor activity, RNA polymerase II-specific; RNA polymerase II cis-regulatory region sequence-specific DNA binding; sequence-specific double-stranded DNA binding
Biological process: regulation of transcription by RNA polymerase II; negative regulation of DNA-templated transcription; regulation of DNA-templated transcription
Cellular component: nucleus; cytoplasm
Genetic constraint (gnomAD): Loss-of-function variants: 7 observed, 7.9 expected, observed/expected ratio (o/e) 0.89, 90% interval 0.5 to 1.62. That is too few expected variants to judge how well the gene tolerates losing a copy. Missense variants: 819 observed, 841.26 expected, observed/expected ratio (o/e) 0.97, 90% interval 0.92 to 1.03. Synonymous variants: 242 observed, 284.06 expected, observed/expected ratio (o/e) 0.85, 90% interval 0.77 to 0.95.
Homologues: Orthologues: chimpanzee ZNF665 (98% identical), macaque ZNF665 (94% identical), mouse Zfp160 (60% identical), rat Zfp160 (59% identical), zebrafish znf646 (22% identical), Drosophila melanogaster zf30C (22% identical), zebrafish si:dkey-89b17.4 (22% identical), zebrafish znf576.1 (20% identical), Drosophila melanogaster CG18011 (19% identical), Drosophila melanogaster CG6791 (18% identical), Drosophila melanogaster CG1602 (16% identical), Caenorhabditis elegans ztf-15 (15% identical), and 23 more. Paralogues in human: ZNF160 (80% identical), ZNF347 (63% identical), ZNF845 (53% identical), ZNF91 (50% identical), ZNF99 (47% identical), ZNF208 (47% identical), ZNF107 (46% identical), ZNF729 (44% identical), ZNF184 (44% identical), ZNF420 (44% identical), ZNF569 (41% identical), ZNF84 (41% identical), and 24 more.